MIR572 (microRNA 572)
Synonyms: hsa-mir-572; MIRN572
Gene: MicroRNA gene on chromosome 4 (11,368,827 to 11,368,921, forward strand). Ensembl gene ENSG00000207716.
Gene Ontology:
Biological process: miRNA-mediated post-transcriptional gene silencing
Cellular component: RISC complex
Diseases named in the same sentence as MIR572 in open-access papers:
MIR572 is named in the same sentence as 5 diseases in open-access papers, as found by Europe PMC text mining. Sharing a sentence is not in itself a finding about the gene and the disease. The quoted sentences say what the papers report.
non-small cell lung carcinoma (1 paper, 2025). A group of at least three distinct histological types of lung cancer, including non-small cell squamous cell carcinoma, adenocarcinoma, and large cell carcinoma. "Previous studies have found MIR572 is upregulated in several types of cancer/malignancy such as non-small cell lung cancer, ovarian cancer, renal cell carcinoma, contributing to malignant development, poor prognosis, and shortened survival time." (PMID 39951158, 2025).
periodontitis (1 paper, 2025). An acute or chronic inflammatory process that affects the tissues that surround and support the teeth. "However, the regulatory role of MIR572 in periodontitis is not clear and requires further investigation to establish how changes in expression of MIR572 is related to periodontitis progression." (PMID 39951158, 2025).
MIR572 also shares sentences with these, for which no sentence is quoted: cancer (1 paper); ovarian carcinoma (1); renal cell carcinoma (1).